TNF (tumor necrosis factor)
Diseases named in the same sentence as TNF in open-access papers (continued):
Sharing a sentence is not in itself a finding about the gene and the disease.
influenza (continued). "In this study, TNF-α response, which seems to be important factor for severe influenza in mammals, was less significant compared with the other cytokines in the chickens infected with Ty/Italy." (PMID 23874602, 2013). "In this study, we built up a simple and lethal influenza-infection mice model to evaluate the effects of TNF inhibitors in influenza virus-induced severe viral pneumonia." (PMID 24373231, 2013). "Since high pre-vaccination plasma levels of TNFα were associated with pTfh activation status and low Ab response to the influenza vaccine, we sought to investigate the effect of TNFα on T and B cells in vitro." (PMID 24236161, 2013). "Thirty-one of 44 patients (70%) who received influenza vaccine were using methotrexate or leflunomide, one patient was on cyclosporine, and five were receiving anti-TNFα drugs at the time of vaccination." (PMID 23510667, 2013). "Overall, the memory T cell response to a prevalent seasonal influenza was a polarized Th1 response, whereas the response to tetanus included a higher proportion of cells with a Thpp-like phenotype (IFNγ−IL-2+TNFα+)." (PMID 23526940, 2013). "ADAMTS7 has also been shown to be upregulated by TNF-α and IL-1β secretion, both of which are activated upon influenza infection." (PMID 22606348, 2012). "IFNγ, KC, and TNF-α all were under expressed in the lungs of influenza infected E2 mice compared to placebo controls." (PMID 22792357, 2012). "Thirteen of the seventeen influenza vaccinated animals demonstrated a RA9-specific CD8 T cell response measuring IFN-γ+/TNF-α+ by ICS assay, ranging from 0.02–0.4%." (PMID 22403659, 2012). "Over-expression of several regulated cytokines including IL-1α, IL-1β, TNF-α, and IFN-γ have been associated with morbidities in influenza infection, and spontaneous pregnancy loss." (PMID 22792357, 2012). "We demonstrate that the majority of RA patients treated with anti-TNF have a decreased influenza-specific effector B cell response that correlates with diminished development of memory B cells and serum antibodies." (PMID 22177419, 2011). "Anti-TNF has minimal effect on the ability of RA patients to achieve the standard 40 or higher protective titer after influenza vaccination; however, lower geometric mean titers (GMT) of antibody have been observed." (PMID 22177419, 2011). "Although a decreased response to the influenza vaccine was observed in RA patients treated with anti-TNF, it is important to emphasize that vaccination did increase serum antibody and presumed protection from infection." (PMID 22177419, 2011). "A limitation of the current study is the inability to adequately assess the various anti-TNF agents individually for their impact on influenza vaccine response." (PMID 22177419, 2011). "RA patients treated with anti-TNF have a diminished B cell and antibody response to the influenza vaccine." (PMID 22177419, 2011). "In this study we specifically examined the impact of anti-TNF treatment of RA patients on influenza-specific B cell responses." (PMID 22177419, 2011). "We have demonstrated that RA patients treated with anti-TNF have impaired B cell and antibody responses to seasonal influenza vaccine." (PMID 22177419, 2011). "This multi-year study was designed to broadly assess the impact of anti-TNF therapy on B cell responses to influenza." (PMID 22177419, 2011). "Peripheral blood samples were obtained from RA patients, including a subset treated with anti-TNF, and from healthy controls to examine influenza-specific responses following seasonal influenza vaccination." (PMID 22177419, 2011). "RA patients treated with anti-TNF exhibit a compromised immune response to influenza vaccine, consisting of impaired effector and consequently memory B cell and antibody responses." (PMID 22177419, 2011). "Although the precise kinetics of induction are unclear, both TNFα and IFNα are also observed in pDC supernatants following influenza infection." (PMID 20532161, 2010).
influenza (continued). "This suggestion is in concordance with previous reports of sufficient humoral response to influenza vaccine in patients treated with TNF-inhibitors." (PMID 20529331, 2010). "The GLA-SE adjuvanted Fluzone vaccine caused no adverse reactions, increased the induction of T helper type 1 (TH1)-biased cytokines such as IFNγ, TNF and IL-2, and broadened serological responses against drifted A/H1N1 and A/H3N2 influenza variants." (PMID 21060869, 2010). "A. paniculata may exert its therapeutic effects against influenza by modulating core targets such as TNF, IL‐6, AKT1, GAPDH, and STAT3." (PMID 41439108, 2025). "Artemisinin-derived artesunate (ART) significantly reduces the expression of TNF-α, IL-6, and IL-1β in the lung tissue of influenza-infected mice by inhibiting the TLR4/NF-κB (p65) axis, with a lung index reduction of over 30%, and significantly improves body weight and survival rate." (PMID 40860873, 2025). "Additionally, TNF acts as a driver of NF-κB signaling during influenza infection and negatively influences TRM cell generation." (PMID 40370445, 2025). "aQIV-vaccinated mice also had no increase in influenza-associated inflammatory cytokines like IL-1β, TNFα, IL-2, and IL-6." (PMID 39975920, 2025). "A. paniculata may exert therapeutic effects against influenza by acting on core targets, such as TNF, IL‐6, AKT1, GAPDH, and STAT3." (PMID 41439108, 2025). "The results suggest that elevated levels of IL-4, IL-6, and IL-10, which are associated with Th2 cell activation, might be related to severe influenza, but the increased TNFα and IFNγ levels also need to be paid attention." (PMID 40558593, 2025). "QIV also showed higher cytokine levels associated with influenza-induced inflammation, such as IL-1β, TNFα, IL-2, and IL-6, similar to the PBS group, which did not control viral replication well." (PMID 39975920, 2025). "Previous research showed that the high level of TNF-α can protect against influenza infection." (PMID 38349151, 2024). "IL-10 exerts anti-inflammatory effects in monocytes, and its elevation may suppress IL-6 and TNF-α production, contributing to the diminished immune response to influenza vaccination observed in older adults." (PMID 39591191, 2024). "Malic acid showed strong negative associations with TNFα, IL-6, and IL-1β cytokine levels upon influenza stimulation." (PMID 39331702, 2024). "Influenza may also influence the development of affective disorders in adults through cytokines released during the immune response, such as interferons, TNF-α, IL-1β, and IL-6, which activate the kynurenine pathway, producing neurotoxic metabolites." (PMID 39206043, 2024). "For example, elderberries were found to show potent anti-influenza activity by affecting the post-infection phase and viral transmission and by modulating the release of the cytokines, interleukin-6 (IL-6), IL-8, and tumor necrosis factor (TNF)." (PMID 38998923, 2024). "In summary, our data suggest that during IAV infection, mature monocytes and DCs accumulate in the nasopharynx, and blood monocytes and DCs function as a general source of TNFα, potentially contributing to the systemic inflammatory effects accompanying influenza infections." (PMID 36752598, 2023). "Ginsenoside Rb1 boosted IgG and antibody subtypes in the H1N1 influenza vaccine, improved survival of mice after virus challenge, attenuated lung histopathological damage, and reduced inflammatory cytokines expression in IL-6 and TNF-α." (PMID 37868069, 2023). "Here, we constructed influenza‐specific IgG landscapes and determined baseline concentrations of cytokines typically associated with chronic inflammation in older adults (TNF‐α, IL‐10, IL‐6, and IFN‐γ) in 30 high and 29 low influenza vaccine responders (HR and LR, respectively)." (PMID 37457646, 2023).
influenza (continued). "Based on the analysis of KEGG enrichment data, the effect of ZSS was mainly correlated with inflammation and immunity such as the IL-17 signaling pathway, TNF signaling pathway, Influenza A, Pertussis, Toll-like receptor signaling pathway, and Th1 and Th2 cell differentiation." (PMID 35815290, 2022). "Furthermore, we found that ONP-302 reduced the levels of MPO, albumin, IL-6, and TNF-α in the lungs of aged, influenza-infected mice." (PMID 35737459, 2022). "Furthermore, we have demonstrated that the overproduction of proinflammatory cytokine TNF-α, in response to influenza-induced IFN-γ, drives lethal lung inflammation." (PMID 36203588, 2022). "As with the PPV-23 vaccine, the response to influenza vaccination may be further blunted in patients who take concomitant immunosuppressants in combination with the TNF inhibitor." (PMID 35214755, 2022). "We also conducted multiplex measurement on cytokines and chemokines at day 7 p.i. in lung tissues using Luminex 200, and similarly, we found significantly higher production of IL-1β, IL-6, TNF-α, IL-10, MCP-1, IP-10, and IFN-γ caused by influenza infection on day 7 p.i.." (PMID 35154087, 2021). "However, some studies have been reported that TNF-α inhibits the replication of viruses such as influenza and hepatitis B virus and serves as the first line of defense against influenza virus infection." (PMID 33924002, 2021). "Additionally, In HIV-infected postmenopausal women, we reported a TNF-α–mediated impairment of CD4 and pTfh function associated with poor antibody responses to influenza vaccination." (PMID 34491910, 2021). "This demonstrated that expression of genes associated with inflammation, TNF, and IL-2 signalling in blood is negatively associated with IgG responses to seasonal influenza vaccination, irrespective of age." (PMID 34726156, 2021). "In addition, both TNFα/NF-κB and influenza infection activity were enriched in the RP patients compared with the recovered patients." (PMID 34394120, 2021). "In addition, gene set enrichment analysis (GSEA) analysis showed the enrichment of TNFα/NF-κB and influenza infection in the RP patients compared with the recovered patients, indicating a hyper-inflammatory immune response in the PBMC of RP patients." (PMID 34394120, 2021). "Thus, signalling through TNF receptor-1 contributed significantly to the severity of the 1918 influenza pandemic; the systemic TNF-α levels were a crucial marker for the progression of the infection." (PMID 34956182, 2021). "Both cell types produce TNF-α following influenza infection." (PMID 32974217, 2020). "TNF-α stimulates IL-1β which exacerbates lung injury during severe influenza but may also have a vital role in lung repair after infection." (PMID 32599823, 2020). "However, it was shown that this fragment enhanced influenza infection as well as expression of inflammatory cytokines TNF-α, IFN-α, IFN-β, IL-12, IL-6, and RANTES, contrasting to the native molecule." (PMID 33542724, 2020). "Proinflammatory cytokines such as interleukin-1β (IL-1β) and tumor necrosis factor–α (TNF-α) are both strongly induced shortly after PR8 influenza infection in mice, and, notably, COUP-TF2 expression is suppressed by these same cytokines in endometrial stromal cells." (PMID 33239293, 2020). "Also, it has been shown that levels of IL-2, IL-6, IL-18, TNFα, IFNγ, ET-1, sICAM-1, and sVCAM-1 are increased in influenza-infected MI patients." (PMID 33193350, 2020). "However, the administration of a detergent split influenza antigen adjuvanted with a TLR4 ligand CRX-601 intranasally led to the induction of harmful antigen specific CD4+TNFα+Th17+ cells in mice." (PMID 33391267, 2020). "In alveolar A549 cells, influenza infection increased the production of pro-inflammatory cytokines and chemokines and the addition of vitamin D either before or after influenza infection reduced gene expression of among other cytokines TNF alpha and IL-6." (PMID 32922301, 2020).
influenza (continued). "Also, the study showed that influenza vaccination reduces the levels of IFNγ, IL-2, and TNFα production and increases the levels of IL-4 in serum." (PMID 33193350, 2020). "Furthermore, elevated plasma levels of TNF-α correlate with lower antibody titers generated in post-menopausal women following vaccination with influenza vaccine." (PMID 31026260, 2019). "Anti‐TNF‐α treatment can reduce influenza vaccine responses." (PMID 31044512, 2019). "When the frequency of CD4 T cells producing IFNγ, IL-2, or TNFα was individually quantified for each of the proteins, the pediatric population had a higher frequency of influenza-specific CD4 T cells producing TNFα compared to IFNγ across all conditions examined." (PMID 30692574, 2019). "Furthermore, plasmacytoid DCs from the elderly are also impaired and produce less TNF-α/IFN-γ in response to TLR7 and TLR9 stimulation, which has been associated with poor antibody response to influenza vaccination as well." (PMID 28769922, 2017). "While associated with pathogenesis, TNF-α neutralization has not been successful in influenza, and, in fact, targeting a single inflammatory mediator has often been met with little success." (PMID 28405622, 2017). "These pathways, including influenza A, herpes simplex infection, antigen processing and presentation, viral myocarditis, tumor necrosis factor (TNF) signaling, graft-versus-host disease, and allograft rejection pathways, were significantly enriched in the present study." (PMID 28977879, 2017). "Infection with highly pathogenic influenza such as H5N1 and H7N9 induces extensive infiltration of macrophages and neutrophils, upregulation of pro-inflammatory cytokines such as TNF-α, IL-1β, IL-6, IL-8 and IP-10, and cell death resulting in severe pulmonary inflammation." (PMID 27315117, 2016). "Interestingly, we observed that TNF-α showed the least contribution in impairing bacterial clearance following influenza." (PMID 27872472, 2016). "For instance, anti-TNF agents currently on the market may prove efficient in controlling the immune response and thus reducing pathology during influenza infections." (PMID 26918620, 2016). "During an influenza infection, activated macrophages in the lungs stimulate cytokines, TNFα and TNFβ, which recruit additional macrophages and other immune system cells that play a role in the recognition of foreign antigens and support proper activation of adaptive response." (PMID 26918620, 2016). "In the short term, TNF/CHP nanoparticles may provide a useful way for developing new nasal influenza vaccines." (PMID 26421290, 2015). "Whilst influenza infection increased the production of pro-inflammatory cytokines and chemokines, as with RSV infection, treatment with vitamin D either before or after influenza infection decreased gene expression of TNF-α, IFN-β, ISG15, CXCL8, IL-6 and RANTES (CCL5)." (PMID 26035247, 2015). "TNF-α has been shown to correlate with morbidity and mortality in influenza-infected subjects." (PMID 26067826, 2015). "As expression of IL-6 and TNFα were induced in our mouse model upon influenza infection, we hypothesized that IL-1β drove the observed inflammation by altering their production." (PMID 24918427, 2014). "This phenomena may have reduced influenza-ability to induce TNF-α, which is one of the most important cytokines released during influenza-induced cytokine storm." (PMID 24978204, 2014). "Because a positive correlation between local cytokine concentration and lung pathology has been observed, we hypothesize that local production of IL-1β, IL-8 and TNF-α is involved in the induction of lung lesions during influenza infection." (PMID 24846450, 2014). "Daniela Damjanovic and his colleagues suggested that TNF-α was dispensable for influenza clearance." (PMID 24725777, 2014). "In addition, we observed increased levels of TNF-α in the BALF at days 7–8-post influenza infection of NKG2A−/− mice compared to WT." (PMID 25251060, 2014).
influenza (continued). "The peak expression of IL-6 and TNFα upon influenza infection was reached faster in C57BL/6 wild type mice at day 1 post infection as compared to day 3 in BALB/c mice, and thus coincided with the earlier response in pulmonary resistance observed in the C57BL/6 strain." (PMID 24918427, 2014). "We subsequently wondered whether due to HIV-1-imposed early restriction on influenza life cycle in macrophages, the ability of this orthomyxovirus to induce the production of pro-inflamatory cytokines, such as TNF-α, would be impaired." (PMID 24978204, 2014). "TNF-α has been reported to exert a defensive effect against influenza infection in vitro." (PMID 24159339, 2013). "In aging HIV-infected and uninfected women, activated CD4 and pTfh cells may compromise influenza vaccine-induced antibody response, for which a mechanism of TNFα-mediated impairment of pTfh-induced IL-21 secretion is postulated." (PMID 24236161, 2013). "The inhibited virus-specific TLR3/7 correlated with reduced influenza replication (M gene) in mice treated with etanercept, which indicated that blocking TNF-α enhanced host control of virus replication, but the elucidation of a possible mechanism requires more experimental investigation." (PMID 24373231, 2013). "The IL-2+ producing T cell bias was not due to overlap of the IL-2+ T cells with T follicular helper (Tfh) cells, as the majority of both IFNγ+TNFα+ and IFNγ−IL-2+TNFα+ influenza-specific cells responding to CA/09 and NC/99 were found within the CXCR5− CD4 T cell population." (PMID 23526940, 2013). "Tumor necrosis factor-alpha (TNF-α) is an important pro-inflammatory cytokine present during influenza infection, but it is unclear whether direct inhibition of TNF-α can elicit protection against influenza infection." (PMID 24373231, 2013). "However, the CA/09ni vdiff pool, representing the peptides least likely to cross-react with epitopes in previous influenza strains, revealed a strongly enhanced response biased towards IFNγ−IL-2+TNFα+ CD4 T cells after PCR-confirmed CA/09 infection." (PMID 23526940, 2013). "In addition to morbidity, both IL-6 and TNF-α levels positively correlated with influenza viral burden." (PMID 24324838, 2013). "The results show that CD8 T cell intrinsic TNF/TNFR2 signaling has a dual role during influenza infection, in enhancing effector function per cell as measured by IFN-γ production and degranulation, as well as in potentiating the contraction of the effector response." (PMID 23874808, 2013). "In addition to IL-6, human serum studies identified TNF-α to be positively correlated with influenza severity." (PMID 24324838, 2013). "The suite of cytokines and chemokines assessed here, namely, TNF-α, IL-6, CCL2, CCL3, CXCL2 and IL-1β, are known to promote the inflammation caused by influenza at early stages of the infection phase, i.e. during the cytokine storm, and have been shown to underpin the pathology and morbidity." (PMID 23577160, 2013). "The short-term influenza-specific effector B cell response was also significantly decreased in RA patients treated with anti-TNF as compared with healthy controls, and correlated with decreased influenza-specific memory B cells and serum antibody present at one month following vaccination." (PMID 22177419, 2011). "In macaques, Mtb and PR8 influenza induced strong TNF production, whereas Schu S4 induced IL-1β." (PMID 21789257, 2011). "The anti-TNF treated patient population may benefit from the high-dose influenza vaccine recently licensed for individuals aged 65 years and older, and warrants further investigation." (PMID 22177419, 2011). "Furthermore, recent European League Against Rheumatism (EULAR) recommendations indicate that influenza vaccination should be strongly considered, and that vaccination can be administered during the use of anti-TNF therapy." (PMID 22177419, 2011).